HTT (huntingtin)
Diseases named in the same sentence as HTT in open-access papers (continued):
Sharing a sentence is not in itself a finding about the gene and the disease.
Huntington disease (continued). "Neurodegenerative diseases are characterized by aggregation of disease‐specific proteins, such as huntingtin in Huntington disease and α‐synuclein in Parkinson disease." (PMID 28680807, 2017). "The major pathological involvement of huntingtin is its defining role in the Huntington’s disease development, which is therefore considered as a single gene degenerative disorder." (PMID 29186753, 2017). "CCT can inhibit amyloid fibre assembly and toxicity of the polyQ extended mutant of huntingtin, the protein responsible for Huntington’s disease." (PMID 28102321, 2017). "Huntington’s disease also exhibits protein inclusions, consisting of a mutant Huntingtin protein that has a polyglutamine expansion." (PMID 28737703, 2017). "In Huntington disease, the huntingtin protein with an extended polyglutamine tract forms insoluble aggregates that are toxic to nerve cells, thereby causing the pathogenesis." (PMID 28680807, 2017). "A well-known and commonly used model to study molecular aspects of Huntington disease are the striatum-derived STHdh cell lines generated from wild type and huntingtin knock-in mouse embryos." (PMID 29203806, 2017). "A variety of mouse models have been developed that express mutant huntingtin (mHTT) leading to aggregates and inclusions that model the molecular pathology observed in Huntington’s disease." (PMID 28099507, 2017). "Many current strategies for the treatment of Huntington’s disease (HD) are focused on development of agents to lower mutant huntingtin (mHTT) protein burden." (PMID 28424652, 2017). "Huntington’s disease is characterized by the formation of intracellular inclusions composed primarily of the ubiquitous protein huntingtin (Htt) and by the subsequent death of striatal medium spiny neurons and cortical pyramidal neurons." (PMID 28923065, 2017). "Several microRNAs have been identified that altered expression of the huntingtin gene, thereby regulating huntingtin aggregation in Huntington’s disease." (PMID 32714581, 2017). "A similar observation has been made when polyQ expanded Huntingtin protein was downregulated using AONs in a Huntington’s disease mouse model." (PMID 28918024, 2017). "In Huntington disease, conformation of huntingtin protein is changed into β-sheet-rich structures that aggregate into potentially toxic oligomeric species and fibril structures." (PMID 28408868, 2017). "Huntington’s disease is an autosomal dominant, neurodegenerative condition caused by a CAG expansion in exon 1 of the gene encoding the Huntingtin (HTT) protein." (PMID 28982376, 2017). "Huntington’s disease develops when the polyglutamine (polyQ) repeat in the Huntingtin (Htt) protein is expanded to over 35 glutamines rendering it aggregation-prone." (PMID 28900136, 2017). "For example, in the 3142-residue-long huntingtin, polyQ repeat encoded by the CAG repeat expansion of the exon 1 varies between 16 and 37 residues in healthy individuals, whereas patients with Huntington’s disease have repeats of >38 glutamine residues." (PMID 29186753, 2017). "Huntington’s disease (HD) is an inherited, autosomal dominant neurodegenerative disease caused by trinucleotide (CAG) repeat expansion in the 5′-end of the huntingtin (htt) gene." (PMID 28846606, 2017). "Huntington's disease (HD) is a monogenic, dominantly inherited neurological disorder caused by a CAG expansion in the huntingtin gene (HTT), and is one of nine neurodegenerative diseases caused by polyglutamine (polyQ) expansion." (PMID 28611571, 2017). "Xbp1 deletion delays progression of Huntington's disease (HD) by increasing autophagy to degrade the mutant Huntingtin (Htt) protein." (PMID 28860159, 2017). "The influence of subject-to-subject variation on N-terminal huntingtin fragments was assessed in human cortex and human striatum using two cohorts of control and Huntington disease subjects." (PMID 28570578, 2017).
Huntington disease (continued). "We report the implementation of QSP to Huntington’s Disease, with the application of a chemogenomics platform to identify strategies to protect neuronal cells from mutant huntingtin induced death." (PMID 29259176, 2017). "The list includes Huntington's disease (HD), which is a monogenic neurodegenerative disorder caused by a CAG-repeat expansion within the huntingtin gene (HTT)." (PMID 28303108, 2017). "A major focus in development of novel therapies for Huntington’s disease (HD) is identification of treatments that reduce the burden of mutant huntingtin (mHTT) protein in the brain." (PMID 28424652, 2017). "Huntington's disease (HD) is a dominantly inherited neurodegenerative disorder characterized by a polyglutamine expansion within the N-terminal region of huntingtin protein (HTT)." (PMID 28533744, 2017). "Huntington’s disease (HD) is an inherited, dominant neurodegenerative disorder caused by an abnormal expansion of CAG triplets in the huntingtin gene (htt)." (PMID 28632780, 2017). "Huntington’s Disease (HD) is a genetically dominant trinucleotide repeat disorder resulting from CAG repeats within the Huntingtin (HTT) gene exceeding a normal range (> 36 CAGs)." (PMID 29209494, 2017). "Huntington’s disease (HD) is a progressive and fatal neurodegenerative disorder caused by an expanded CAG repeat in the huntingtin gene." (PMID 28701700, 2017). "Huntington’s disease (HD) is an autosomal dominant neurodegenerative disorder resulting from a polyglutamine expansion in the huntingtin (HTT) protein." (PMID 28603746, 2017). "Huntington disease (HD) is a monogenic neurodegenerative disorder triggered by trinucleotide expansions in the huntingtin gene causing corticostriatal dysfunction and leading to abnormal muscle coordination (choreic movements), mental decline, and behavioral symptoms." (PMID 26697081, 2016). "Using a yeast model of Huntington’s disease, we show that contrary to expectation, aggregation of mutant huntingtin is exacerbated and activation of the unfolded protein response pathway is dampened under dietary restriction." (PMID 27633120, 2016). "Previously, we found that a prion-like domain in the N-terminus of FUS/TLS mediates co-aggregation between FUS/TLS and mutant huntingtin, the gene product of Huntington’s disease (HD)." (PMID 27739513, 2016). "In Huntington disease, HTT protein is modified and it increases the rate of apoptosis, also provides protection against cancer." (PMID 27875990, 2016). "Huntington's disease (HD) is an autosomal dominant, neurodegenerative disorder caused by an expansion of CAG repeats in the gene (HTT) encoding huntingtin (HTT), a protein involved in vesicle dynamics and intracellular transport." (PMID 27995895, 2016). "The Huntington's Disease protein, mutant huntingtin with expanded polyQ (mHtt), is known to form protein aggregates that are subject to autophagic clearance, and therefore can be used as another indicator of autophagy flux." (PMID 26814436, 2016). "Huntington's disease is a fatal autosomal genetic disorder characterized by an expanded glutamine-coding CAG repeat sequence in the huntingtin (Htt) exon 1 gene." (PMID 28096892, 2016). "Huntington's disease (HD), an autosomal dominantly inherited neurodegenerative disease, is caused by an expansion mutation in CAG triplet repeat number in exon 1 of the huntingtin (HTT) gene." (PMID 27920719, 2016). "HDAC4 inhibition has demonstrated significant effects to increase the stability of MAP1S, MAP1S-mediated autophagy flux and degradation of mutant Huntingtin aggregates that are directly impact Huntington's disease." (PMID 27236336, 2016). "In Huntington’s disease (HD), neurotoxicity correlates with an increased aggregation propensity of a polyglutamine (polyQ) expansion in exon 1 of mutant huntingtin protein (mHtt)." (PMID 27751235, 2016).
Huntington disease (continued). "Huntington’s disease (HD) is an autosomal–dominant, progressive neurodegenerative disease associated with an expanded CAG repeat in the huntingtin (Htt) gene." (PMID 28018188, 2016). "Huntington ́s disease (HD) is a hereditary neurodegenerative disease resulting from an expanded polyglutamine sequence (poly-Q) in the protein huntingtin (HTT)." (PMID 27820862, 2016). "Huntington’s disease (HD) is a dominantly inherited, progressive neurodegenerative disorder caused by a CAG repeat expansion within exon 1 of HTT, encoding huntingtin." (PMID 26864449, 2016). "Huntington’s disease (HD) cellular pathology is characterised by the aggregation of mutant huntingtin (mHTT) protein into inclusion bodies." (PMID 27196694, 2016). "In models of Huntington's disease, mutant huntingtin protein interferes with the TORC1-CREB interaction to repress transcription of brain-derived neurotrophic factor, and also the depletion of CRTC1 contributes to Huntington's disease." (PMID 27034888, 2016). "Of particular interest is Huntington's disease, a debilitating heritable condition, brought about by an increase in the number of glutamine repeats (polyQ) in the gene huntingtin." (PMID 27402594, 2016). "It is also intriguing that in our study a variant in HAP was found, whereas in similar series heterozygous variants in huntingtin (HTT) have been described, further reinforcing the links between Huntington’s disease and Rett syndrome." (PMID 27541642, 2016). "Huntington’s disease (HD) is a progressive and fatal neurodegenerative disorder caused by abnormal expansion of the CAG repeat in the huntingtin gene (HTT)." (PMID 27390852, 2016). "For example the MID1 protein binds to mutant huntingtin (HTT) RNA, which is linked to Huntington's disease (HD), at its CAG repeat region and induces protein synthesis of mutant protein." (PMID 27774050, 2016). "Hypothalamic pathology, metabolic dysfunction and psychiatric symptoms are part of Huntington disease (HD), which is caused by an expanded CAG repeat in the huntingtin (HTT) gene." (PMID 27334347, 2016). "The first mouse model of Huntington’s disease, the R6/2, expressing HTT exon 1 under control of the human promoter, followed rapidly in 1996 and remains a mainstay in the field thanks to its robust phenotype and rapid progression." (PMID 27421790, 2016). "Mutant huntingtin (Htt) forms, the main source of neurotoxic activities of Huntington disease (HD), are sensitive to beclin 1 level as demonstrated by the increased accumulation of Htt upon beclin 1 deficiency." (PMID 26999089, 2016). "Age of Huntington's disease (HD) motoric onset is strongly related to the number of CAG trinucleotide repeats in the huntingtin gene, suggesting that biological tissue age plays an important role in disease etiology." (PMID 27479945, 2016). "Huntington's disease (HD) is a hereditary neurodegenerative disorder, caused by an expansion of CAG triplet repeats in the Huntingtin gene on chromosome 4." (PMID 28018198, 2016). "Huntington’s disease (HD) is a fatal, autosomal dominant disorder caused by a pathologic expansion of CAG repeats in the IT15 gene, which encodes the ubiquitously expressed huntingtin protein." (PMID 25941073, 2016). "Here, we studied the effect of pharmacological and genetic manipulation of glycation on huntingtin (HTT), the causative protein in Huntington’s disease (HD)." (PMID 27857176, 2016). "Huntington’s disease (HD) is an incurable, autosomal dominant neurodegenerative disorder that is caused by a CAG repeat expansion in exon 1 of the huntingtin (HTT) gene." (PMID 27170315, 2016). "Huntington Disease (HD) is a fatal autosomal dominant genetic disorder that is characterized by CAG trinucleotide repeats in the huntingtin (Htt) exon 1 gene." (PMID 28096892, 2016).
Huntington disease (continued). "The Huntington’s disease (HD) protein, huntingtin (HTT), is a large protein consisting of 3144 amino acids and has conserved N-terminal sequences that are followed by a polyglutamine (polyQ) repeat." (PMID 27203582, 2016). "For Huntington disease (HD), mutant huntingtin (mHTT) has been observed in neuronal grafts in patients, an observation similar to that made for α-syn in PD, although in this case the deposits were extracellular." (PMID 26820848, 2016). "The 17 amino acids in the N-terminal region of huntingtin (HTT) are conserved in a wide range of species and are followed by a polyglutamine repeat whose expansion causes selective neurodegeneration in Huntington’s disease (HD)." (PMID 27203582, 2016). "Huntingtin-associated Protein 1 (HAP1) is a ~100 kDa protein that was first identified in a screen for proteins that interact with the Huntington’s disease (HD) gene product, huntingtin (HTT)." (PMID 27737633, 2016). "The abundant accumulation of inclusion bodies containing polyglutamine-expanded mutant huntingtin (mHTT) aggregates is considered as the key pathological event in Huntington’s disease (HD)." (PMID 26450664, 2015). "Huntington's disease, the most common of the polyQ disorders, is caused by expansion of CAG repeats in exon 1 of the HTT gene, which encodes the huntingtin protein." (PMID 25873774, 2015). "Subsequently, it has been shown that, in transgenic Huntington’s disease mouse models, mutant HTT alters tau phosphorylation which is known to be a characteristic of insoluble paired helical filaments that form neurofibrillary tangles." (PMID 25953777, 2015). "Aberrant activation of SUMO-1 contributes to Huntington’s disease by increasing the stability of polyglutamine-repeat protein aggregates in huntingtin protein." (PMID 25734985, 2015). "In a neuron model of Huntington’s disease, pharmacologically inhibiting S1P-lyase protected neurons from mutant huntingtin-induced neurotoxicity." (PMID 26477494, 2015). "In several diseases, there is accumulation of protein aggregates named huntingtin, parkin and beta amyloid plaque in Huntington’s disease, Parkinson’s disease and Alzheimer’s disease, respectively due to lack of autophagy." (PMID 27551448, 2015). "Our VHH are capable of binding wild-type and mutant human huntingtin under native and denatured conditions and can be used in Huntington disease studies as a novel antibody that is easy to produce and manipulate." (PMID 25294428, 2015). "To study the biology of Huntington’s disease in cell culture, we used three different models that express the exon 1 of huntingtin." (PMID 26268247, 2015). "Overexpression of TFEB was found to decrease the accumulation of polyglutamine-containing huntingtin aggregates in a rat striatal cell model of Huntington’s disease and reduce huntingtin aggregate formation in Neuro2a cells subjected to oxidative stress." (PMID 25790376, 2015). "Another disease that causes impairment of movement is Huntington's disease (HD), an autosomal dominant neurodegenerative disorder caused by an expanded CAG repeat in the coding region of the huntingtin gene." (PMID 26770022, 2015). "Modeling Huntington's disease in C. elegans requires the expression of a recombinant fragment of Huntingtin protein (Htt) containing multiple polyglutamine (polyQ) repeats in either muscle or neuronal cells using appropriate tissue-specific promoters." (PMID 28031870, 2015). "Huntington ́s disease (HD) is an inherited neurodegenerative disease, caused by a CAG triplet repeat expansion in the gene encoding huntingtin." (PMID 26431314, 2015). "A similar mechanism exists in Huntington’s disease, where sequestration of mutant huntingtin in inclusion bodies correlates with better neuron health." (PMID 25996830, 2015). "Huntington's disease is triggered by misfolding of fragments of mutant forms of the huntingtin protein (mHTT) with aberrant polyglutamine expansions." (PMID 25861763, 2015).
Huntington disease (continued). "Among them, a polyglutamine region that is present in huntingtin is known to exhibit a correlation between the length of the chain and the severity as well as the earliness of the onset of Huntington disease." (PMID 26495838, 2015). "Huntingtin—the protein that is aberrant in Huntington Disease—regulates apical vesicular trafficking to help establish apical-basolateral polarity during the development of mammary epithelia." (PMID 25942483, 2015). "In Huntington’s disease an elongated stretch of polyglutamines within the protein Huntingtin leads to increased aggregation propensity." (PMID 26335097, 2015). "In Huntington’s disease, Huntingtin (Htt), a protein with yet unattributed function, exhibits a tendency to aggregate within cells if mutated." (PMID 26335097, 2015). "Huntingtin (HTT), the protein mutated in Huntington disease, acts as a molecular scaffold and promotes intracellular dynamics." (PMID 25942483, 2015). "In Huntington’s disease, huntingtin with expanded poly glutamine repeats (polyQ) predominates in neuronal inclusions." (PMID 26293199, 2015). "Huntington's disease (HD) results from an increased length of a polyglutamine stretch in the N terminus of Huntingtin protein, due to expanded CAG repeat in the first exon of the IT15/huntingtin gene." (PMID 25611391, 2015). "Quantitation of huntingtin protein in the brain is needed, both as a marker of Huntington disease (HD) progression and for use in clinical gene silencing trials." (PMID 26174131, 2015). "Huntington’s disease (HD) is an autosomal-dominant neurodegenerative disorder resulting from expansion of CAG repeats in the Huntingtin (HTT) gene." (PMID 26636336, 2015). "Huntington disease (HD; OMIM 143100), a progressive neurodegenerative disorder, is caused by an expanded trinucleotide CAG (polyQ) motif in the HTT gene." (PMID 25993131, 2015). "For Huntington's disease (HD), models expressing human huntingtin with an expanded polyglutamine region develop a progressive syndrome akin to HD." (PMID 28031870, 2015). "Huntington’s disease (HD) is a fatal, autosomal dominant neurodegenerative condition caused by a CAG repeat expansion in exon 1 of the huntingtin (HTT) gene on chromosome 4." (PMID 26529236, 2015). "Modified cell lines are widely used as models for Huntington's disease for preclinical screening of drugs to study their ability to suppress the expression of huntingtin." (PMID 27335679, 2014). "In humans, longer polyglutamine expansion in huntingtin is well known to result in earlier onset of Huntington's disease and lower life expectancy." (PMID 25101108, 2014). "When proteins extracted from the brain of patients with Huntington disease are analyzed by Western blotting, monomeric expanded huntingtin is replaced by a smear extending above the expected position of the monomer." (PMID 24961702, 2014). "This genetic abnormality results in the expression of an expanded polyglutamine tract in huntingtin protein, which can aggregate in neuronal nuclei and dystrophic neuritis in Huntington's disease brains." (PMID 24868314, 2014). "This review critically analyses the molecular biology techniques for detection and quantitation of huntingtin and evaluates the various animal species for use as models for Huntington's disease." (PMID 27335679, 2014). "The length of the huntingtin (HTT) CAG repeat is strongly correlated with both age at onset of Huntington’s disease (HD) symptoms and age at death of HD patients." (PMID 24751919, 2014). "When the inclusions found in the brain of patients with Huntington disease are incubated in pure formic acid, they release multiple N-terminal fragments of expanded huntingtin as well as oligomers and polymers of the protein." (PMID 24961702, 2014). "Presence of aggregated N-terminal huntingtin fragments in nuclei has also been reported in cultured cells expressing expanded intact huntingtin and in Huntington disease brain." (PMID 24961702, 2014).